SDHC (succinate dehydrogenase complex subunit C)
Diseases named in the same sentence as SDHC in open-access papers (continued):
Sharing a sentence is not in itself a finding about the gene and the disease.
cervical cancer (1 paper, 2024). A primary or metastatic malignant neoplasm involving the cervix. "Our data provide evidence that Th17 cells induced the expression of miR‐142‐5p in cervical cancer cells and identified SDHC and SDHD as new targets of miR‐142‐5p responsible for enhanced migration and invasion." (PMID 37899663, 2024). "Taken together, our data clearly showed that Th17‐induced enhanced migration and invasion of cervical cancer cells is dependent on miR‐142‐5p‐mediated suppression of SDHC and SDHD." (PMID 37899663, 2024). "In line with this, our knock down of SDHC or SDHD in cervical cancer cells increased the expression of vimentin, ZEB1 and TWIST, but reduced e‐cadherin." (PMID 37899663, 2024). "To investigate how miR‐142‐5p contributes to enhanced migration and invasiveness of cervical cancer cells we performed an in‐silico target prediction that identified subunits of the succinate dehydrogenase (SDH) complex with miR‐142‐5p binding sites in their 3′UTRs including SDHC and SDHD." (PMID 37899663, 2024). "Next, we analyzed the impact of Th17 cells on the expression of SDHC and SDHD in cervical cancer cells." (PMID 37899663, 2024). "To analyze the relevance of SDHC and SDHD for migration of cervical cancer cells we knocked down SDHC or SDHD with two specific siRNAs in three cervical cancer cells." (PMID 37899663, 2024). "In our study, we identified that Th17 cells decreased the expression of SDHC and SDHD in cervical cancer cells resulting in diminished SDH complex activity that was mediated by miR‐142‐5p and validated SDHC and SDHD as new targets of miR‐142‐5p." (PMID 37899663, 2024). "In summary, we could show that Th17 cells reduced the expression of SDHC and SDHD as well as activity of the SDH complex in cervical cancer cells." (PMID 37899663, 2024).
colorectal adenocarcinoma (1 paper, 2021). The most common type of colorectal carcinoma. "Conversely, these isoforms are over-expressed in different tumor lines, such as HCT-15 colorectal adenocarcinoma cells, where the increase in the expression of SDHC Δ3 and Δ5 ASVs was found associated with reduced SDH activity and increased production of O2−." (PMID 34679737, 2021).
diabetes (1 paper, 2021). "Hexokinase 2 (HK2; FC = −3.4), succinate dehydrogenase complex, subunit C (SDHC; FC = −3.1), isocitrate dehydrogenase 1 (IDH1; FC = −1.8), and pyruvate kinase muscle (PKM; FC = 1.5) were all downregulated in individuals with diabetes." (PMID 34690929, 2021).
familial hypercholesterolemia (1 paper, 2024). An inheritable form of hyperlipidemia, in which there are excess lipids in the blood.
gastric adenocarcinoma (1 paper, 2022). "Three Subjects with VUS were identified: SDHA: SDHA c.1579C>T in Subject 11, or SDHC:c.430G>C in Subjects 12 and 13, with respectively the diagnosis of gastric adenocarcinoma, retroperitoneal leiomyosarcoma, and uterine adenosarcoma." (PMID 36091175, 2022).
leiomyosarcoma (1 paper, 2024). An uncommon, aggressive malignant smooth muscle neoplasm, usually occurring in post-menopausal women.
lobular breast cancer (1 paper, 2019). "The SDHC mRNA level was inversely associated with the EMT8 score in each subgroup of the n = 204 cohort (with Rho between − 0.431 and − 0.373), except for lobular breast cancer." (PMID 31164982, 2019).
malaria (1 paper, 2020). Malaria is a serious and sometimes fatal disease caused by a parasite that commonly infects a certain type of mosquito which feeds on humans. "All human proteins in this cluster were known to be drug targets and there were 19 associations of these five human proteins (SUCLG1, SDHA, SDHB, SDHC, and SDHD) and five malaria proteins (PVX_096130, PVX_123265, PVX_003675, PVX_113540, and PVX_003575)." (PMID 32075230, 2020).
myasthenia (1 paper, 2025). "We performed an enzyme immunoassay of plasma to compare the concentration of proteins: COQ10A, GAPDH1, and SDHC in patients with myasthenia compared to controls." (PMID 40843740, 2025).
myasthenia gravis (1 paper, 2025). Myasthenia gravis (MG) is a rare, clinically heterogeneous, autoimmune disorder of the neuromuscular junction characterized by fatigable weakness of voluntary muscles. "We conducted a study of plasma expression of microRNA hsa-miR-181a-5p, hsa-miR-194-5p, and hsa-miR-148a-3p, as well as three proteins—COQ10A, GAPDH1, and SDHC—in patients with an established diagnosis of myasthenia gravis in comparison with healthy volunteers." (PMID 40843740, 2025).
myeloid leukemia (1 paper, 2021). A clonal proliferation of myeloid cells and their precursors in the bone marrow, peripheral blood, and spleen. "With this in mind, we investigated the levels of SDHC variants and the oxidative mitochondrial metabolism in myeloid leukemia K562 cells over-expressing GATA-1 isoforms." (PMID 34679737, 2021).
paraganglioma type 3 (1 paper, 2014). "For SDHC Pro110Ser and Met164Leu, clinical presentation and family history did not indicate familial paraganglioma type 3." (PMID 24466223, 2014).
thyroid cancer (1 paper, 2019). "In addition, somatic SDHC mutations were also detected in 5% of sporadic thyroid cancer cases in a cohort study." (PMID 31817761, 2019).
thyroid tumor (1 paper, 2015). A benign or malignant neoplasm affecting the thyroid gland. "However, how exactly this large duplication (including SDHC and other genes) impacts tumorigenesis warrants further investigation, given that the TCGA thyroid tumor dataset as a whole showed an overall decrease of SDHC expression compared with their normal tissues." (PMID 25694510, 2015). "Compared with available normal thyroid tissues (n=57), thyroid tumor tissue (n=484) showed significant reduction in PTEN, SDHC, and SDHD gene expression (P<0.001)." (PMID 25694510, 2015).
tumor (64 papers, 2006 to 2025). "SDH deficient (dSDH) wtGIST is the most common subcategory of wtGIST, and these tumours are driven by inherited germline mutations in one of the SDHx genes (SDHA/B/C/D) or can occur sporadically following epigenetic silencing of the SDHC gene." (PMID 33443647, 2021). "SDH-deficient tumours are most commonly associated with a germline SDH subunit gene (SDHA/B/C/D) mutation but can also be associated with epigenetic silencing of the SDHC gene." (PMID 31308404, 2019). "Two of the cases with a germline SDHC mutation had multiple tumours including case #004." (PMID 31308404, 2019). "SDHC activation is a significant event during the electron transport chain, and the function of the SDHC Δ5 variant may be significant for the differentiation of tumor cells." (PMID 25435987, 2015). "Initially, a large somatic genomic deletion on 1q, encompassing the SDHC gene locus, was postulated as the molecular driver of this tumor syndrome." (PMID 39927693, 2025). "Germline testing is recommended for SDHA, SDHB, SDHC, and SDHD across all ages and tumor types in the setting of SDH‐deficient staining and/or when an SDHx PV is identified in the tumor." (PMID 39927693, 2025). "Drug screening and RNA sequencing were carried out to reveal the tumor suppressor mechanism of SDHC." (PMID 38844980, 2024). "In breast cancer, downregulation of SDHC promote tumor development by promoting the occurrence of epithelial mesenchymal transformation and structural reconstruction of mitochondrial organelles." (PMID 38844980, 2024). "The results demonstrated a significantly lower expression of SDHC in CRC tissues compared to paired peri-tumor tissues." (PMID 38844980, 2024). "Assessing these differences for each individual gene in association with tumor location shows that proportionally more HNPs were reported for European patients with PVs in SDHA, SDHB, SDHC, and SDHD than for Asian patients." (PMID 38481600, 2024). "In this study, we used GEO datasets, TCGA database and mitochondrial genes to identify the key molecule of tumor metastasis, SDHC." (PMID 38844980, 2024). "Tumour SDHC promoter methylation was identified in 12 cases of dSDH wtGIST of which nine had no identifiable germline SDHx mutation." (PMID 36198483, 2023). "Of the 35 tumours analysed for genetic variants, 25 carried variants in SDHD, 7 in SDHB and 1 in SDHC." (PMID 36178902, 2022). "We describe the long-term culture of chiefly head and neck paragangliomas using primary tumour tissue from anonymous donors who carried succinate dehydrogenase subunit B (SDHB), subunit C (SDHC), subunit D (SDHD) or undefined gene variants." (PMID 36178902, 2022). "We discover that loss of certain oxidative phosphorylation (OXPHOS) genes (e.g. SDHC) improves tumour cell growth in hypoxia-glucose, but reduces growth in normoxia, indicating a metabolic switch in OXPHOS gene function." (PMID 34021238, 2021). "When ROS scavengers were overexpressed, expression of sdhC-RNAi blocked Hipk-induced tumor-like growth to a certain extent." (PMID 33199523, 2020). "The results from previous studies also reported that the expression of SDHC was reduced in tumor tissues." (PMID 33053772, 2020). "Taken together, mefloquine inhibits ESCC tumor growth by inducing mitochondrial autophagy and SDHC plays a vital role in MQ-induced anti-tumor effect on ESCC." (PMID 32850358, 2020). "Given that high ROS potentiates JNK-dependent MMP1 induction, most of the RNAi lines tested (ATPsynβ-RNAi, sdhC-RNAi and cox5A-RNAi) need to be accompanied by simultaneous overexpression of ROS scavengers in order to reduce Hipk tumor growth." (PMID 33199523, 2020). "HPV+ HNSCC patients with tumours exhibiting low SDHC expression had better overall five-year survival outcomes than HPV+ HNSCC patients with tumours exhibiting high SDHC expression (p = 0.011, FDR = 0.043)." (PMID 31968678, 2020).
tumor (continued). "To further investigate the role of SDHC in ESCC tumor growth, we transfected KYSE150 and KYSE450 cells with shSDHC." (PMID 32850358, 2020). "The authors recommend that whenever possible, cases with SDHC promoter hypermethylation should be analysed by RT-PCR of both tumour and adjacent normal tissue to confirm silencing of SDHC in the tumour tissue." (PMID 31308404, 2019). "All 6 SDHC epimutation cases presented with SDH deficient wtGIST and 3/6 cases had multiple primary tumours." (PMID 31308404, 2019). "The SDH complex consists of four subunits (SDHA, SDHB, SDHC, and SDHD), and a deficiency of this enzyme is known to activate tumor formation through dysregulation of HIF activity." (PMID 31817761, 2019). "Collectively, this study estimated that ~ 11% of PPGL patients carry germline mutations in the four genes (SDHA, SDHB, SDHC, SDHD; SDHx) encoding SDH subunits, and ~ 5% of PPGL patients have tumor DNA carrying the novel MAML3 translocation." (PMID 31234811, 2019). "The most common and closest change detected by tumor genetic studies is the deletion of the 1cen-q21 chromosomal region involving the SDHC gene." (PMID 31372201, 2019). "WGS data was analysed for three cases with tumour SDHC hypermethylation for whom sufficient DNA was available (cases; #002, #021 and #022)." (PMID 31308404, 2019). "The majority of patients (94%, 32/34) identified with SDHC hypermethylation had a dSDH-wtGIST and 53% (18/34) of these cases also had an additional tumour(s)." (PMID 31308404, 2019). "SDHC promoter methylation analysis of 32 paraffin embedded tumours (including 15 GIST and 17 PPGL) was performed using a pyrosequencing technique and correlated with SDHC gene expression." (PMID 31308404, 2019). "Methylation array (Illumina 450k) data for these 25 tumours was accessed and beta values for 13 SDHC promoter probes inspected." (PMID 31308404, 2019). "In conclusion, the results from our literature review, experimental studies and interrogation of the TCGA data, suggest that SDHC epimutations are rare in tumours other than wtGIST and PPGL." (PMID 31308404, 2019). "Biallelic inactivation of one of the four SDH subunit genes (SDHA, SDHB, SDHC, SDHD) is the most common mechanism causing SDH deficient (dSDH) tumours." (PMID 31308404, 2019). "Studies are currently underway to clarify the manner in which SDHC ASVs affect genes, leading to tumor formation." (PMID 25435987, 2015). "RET Tyr791Phe and SDHC Pro110Ser were verified by Sanger sequencing in both blood and tumour tissues." (PMID 23781326, 2013). "This case also had a P/LPGV in SDHC that was identified on the tumor profiling." (PMID 41465149, 2025). "Our findings indicated that the tumor suppressor SDHC could repress fatty acid synthesis by decreasing the expression of ALDH3A2 and simultaneously promote FAO by upregulating the FAO-related enzymes ACOX1 and CPT1A through the PI3K/AKT signaling axes." (PMID 38844980, 2024). "In order to further confirm the impact of SDHC on tumor invasion and metastasis through lipid accumulation, we utilized orlistat, a fatty acid synthase inhibitor, to decrease the presence of lipid droplets in SDHC knockdown cells." (PMID 38844980, 2024). "Hypermethylation was higher in SDHB-mutated PPGL when compared to SDHA, SDHC and SDHD cases, which may explain the greater metastatic potential of SDHB-mutated tumours." (PMID 35938916, 2022). "Therefore, we decided to further validate SDHC to demonstrate the influence of mitochondrial gene expression on tumour cell growth in hypoxia." (PMID 34021238, 2021). "This indicated that SDHC plays an important role in tumor growth." (PMID 32850358, 2020). "We identified 4 cases of tumour SDHC promoter methylation with no detectable germline or somatic SDHC mutations." (PMID 31308404, 2019).
tumor (continued). "In the absence of a detectable in cis or in trans genetic variant in these cases, low level postzygotic tissue mosaicism for SDHC promoter hypermethylation, provides an alternative hypothesis for this multiple tumour phenotype at a young age." (PMID 31308404, 2019). "If an SDHC epimutation is diagnosed, somatic tumour sequencing should be performed to identify a co-existing somatic SDHx mutation, which may affect the efficacy of any potential demethylating therapy." (PMID 31308404, 2019). "Importantly, a number of potential limitations in the diagnosis of SDHC methylation using pyrosequencing methods on FFPE tumour tissue, were encountered over the course of this study." (PMID 31308404, 2019). "Tumour sequencing was performed on 4/6 (#001, #002, #003, #004) cases with evidence of SDHC hypermethylation and no somatic SDHx variants were detected." (PMID 31308404, 2019). "Notably, EPAS1 was nominated as the top-ranking SDHC-loss MR gene, in contrast to the SDH-loss human PPGL tumor analysis." (PMID 31234811, 2019). "SDHC promoter methylation was identified in 6 (18.7%) tumours." (PMID 31308404, 2019). "A search of PubMed (using the terms SDHC and methylation or epimutation) identified 8 publications containing 34 cases of SDHC promoter region hypermethylation in a variety of tumour types including dSDH wtGIST, sympathetic (PGL) and parasympathetic (HNPGL) paragangliomas." (PMID 31308404, 2019). "This would be consistent (though not proven) with a two hit model of tumourigenesis in which SDHC hypermethylation resulted in silencing of the wild-type allele in the tumour." (PMID 31308404, 2019). "Specific genotype-tumour risk associations provides a basis for novel investigative strategies into succinate dehydrogenase-related mechanisms of tumourigenesis and the development of personalised management for SDHB/SDHC/SDHD mutation carriers." (PMID 29386252, 2018). "Analysis of HIF-1α protein expression revealed that the SDHC-mutated cell line contains mixed populations of tumor cells, i.e. 72% were negative for HIF-1α protein expression but about 28% of cells accumulate nuclear HIF-1α even under normoxic conditions." (PMID 28036268, 2017). "Additionally, knockdown of key mitochondrial complex I (NDUFV1) and complex II (SDHC) subunits by shRNA in B16ρ0 cells abolished or significantly retarded their ability to form tumours." (PMID 28195532, 2017). "In the present study, to explore the mechanism of the PGL tumor development, the occurrence of SDHC gene ASVs was investigated, in particular, deleted exon 5 ASVs, which may induce frameshift mutations." (PMID 25435987, 2015). "The SDHC gene has been shown to be a major tumor suppressor gene in mitochondria." (PMID 25010005, 2014). "Thus, the improvement in fitness in hypoxia from the loss of SDHC and other OXPHOS genes may be dependent on the degree to which tumour cell proliferation is coupled to mitochondrial function." (PMID 34021238, 2021). "Therefore, if SDH genetic testing of an SDHB-immunonegative tumor does not show a mutation, SDHC promoter methylation, VHL, and/orNF1 molecular testing is recommendable." (PMID 34181326, 2021). "Besides, the tumor has an SDHA or SDHC alteration is also possible." (PMID 33612108, 2021). "Thus, SDHC alternative splicing in tumor cells may reflect pre-existing alternative splicing mechanisms present in the parent cells." (PMID 25435987, 2015). "Anwar et al20 identified 17 genes in 90% of the Ghanian tumours that had recurrent CNV’s with the most frequent gains observed in RECQL4 (8q24.3) and SDHC (1q23.3) genes in 50% and 60% of cases, respectively." (PMID 40813389, 2025). "In summary, our investigation explored the roles of SDHC in CRC, uncovering its potential as both a tumor suppressor and a prognostic predictor." (PMID 38844980, 2024).